MAML3 (mastermind like transcriptional coactivator 3)
Description:
Acts as a transcriptional coactivator for NOTCH proteins. Has been shown to amplify NOTCH-induced transcription of HES1.
Synonyms: Mam-3; KIAA1816; MAM2; CAGH3; GDN; ERDA3; MAM-2; TNRC3
Tractability: No criterion of Open Targets' tractability assessment is met for any kind of drug.
Gene: Protein-coding gene on chromosome 4 (139,716,753 to 140,154,212, reverse strand). Ensembl gene ENSG00000196782.
Subcellular location: Nucleus speckle
Subcellular location (Human Protein Atlas): Nuclear speckles
Pathways (Reactome):
Signal Transduction: NOTCH1 Intracellular Domain Regulates Transcription; NOTCH2 intracellular domain regulates transcription; NOTCH3 Intracellular Domain Regulates Transcription; NOTCH4 Intracellular Domain Regulates Transcription; Pre-NOTCH Transcription and Translation
Developmental Biology: Differentiation of naive CD4+ T cells to T helper 2 cells (Th2 cells); Formation of paraxial mesoderm; Regulation of gene expression in late stage (branching morphogenesis) pancreatic bud precursor cells
Disease: Constitutive Signaling by NOTCH1 HD+PEST Domain Mutants; Constitutive Signaling by NOTCH1 PEST Domain Mutants
Gene expression (Transcription): Notch-HLH transcription pathway; RUNX3 regulates NOTCH signaling
Gene Ontology:
Molecular function: protein binding; transcription coactivator activity
Biological process: Notch signaling pathway; positive regulation of transcription by RNA polymerase II; positive regulation of transcription of Notch receptor target
Cellular component: nuclear speck; nucleus; nucleoplasm
Genetic constraint (gnomAD): Loss-of-function variants: 24 observed, 103.21 expected, observed/expected ratio (o/e) 0.23, 90% interval 0.17 to 0.33. The upper end of that interval is the gene's LOEUF score, 0.33, which puts it in group 1 of 6, group 1 being the genes least tolerant of losing a copy. Missense variants: 1,311 observed, 1,499.8 expected, observed/expected ratio (o/e) 0.87, 90% interval 0.83 to 0.92. Synonymous variants: 500 observed, 571.67 expected, observed/expected ratio (o/e) 0.87, 90% interval 0.81 to 0.94.
Homologues: Orthologues: chimpanzee MAML3 (99% identical), macaque MAML3 (98% identical), rabbit MAML3 (91% identical), pig MAML3 (91% identical), rat Maml3 (89% identical), mouse Maml3 (88% identical), dog MAML3 (87% identical), tropical clawed frog maml3 (64% identical), zebrafish maml3 (44% identical). Paralogues in human: MAML1 (32% identical), MAML2 (26% identical).
Diseases named in the same sentence as MAML3 in open-access papers:
MAML3 is named in the same sentence as 47 diseases in open-access papers, as found by Europe PMC text mining. Sharing a sentence is not in itself a finding about the gene and the disease. The quoted sentences say what the papers report.
pheochromocytoma (7 papers, 2018 to 2025). "Apart from kinases activated by gene fusions, MAML3 fusion gene could upregulate the Wnt signalling pathway and may be associated with an increased growth rate in pheochromocytomas and paragangliomas." (PMID 40615663, 2025). "Succinate dehydrogenase (SDH) loss and mastermind-like 3 (MAML3) translocation are two clinically important genetic alterations that correlate with increased rates of metastasis in subtypes of human paraganglioma and pheochromocytoma (PPGL) neuroendocrine tumors." (PMID 31234811, 2019). "The Wnt cluster contains mostly pheochromocytomas with somatic fusions involving the Mastermind Like Transcriptional Coactivator 3 (MAML3) gene as well as Cold Shock Domain Containing E1 (CDSE1) mutations." (PMID 33768452, 2021). "Additionally, activating mutations of Wnt-signalling pathway or its components, including somatic mutations of CSDE1 (cold shock domain containing E1) and MAML3 (mastermind like transcriptional coactivator 3) genes are known as cluster 3 in phaeochromocytomas and paragangliomas." (PMID 33114456, 2020).
gastric cancer (5 papers, 2019 to 2022). A primary or metastatic malignant neoplasm involving the stomach. "The methylation of XKR6, CCDC57, MAML3, SDC2, and CLIP4 is associated with age and tumor location in gastric cancer." (PMID 33575272, 2020). "A recent study performed an integrated analysis and revealed that miR-20°c-3p and miR-52°c-3p could intermediate core-regulatory genes including MAML3 to affect stemness and metastasis in gastric cancer." (PMID 36061051, 2022). "In human, the miR-2392 can regulate its target gene MAML3 and WHSC1 to suppress metastasis and epithelial-mesenchymal transition in gastric cancer." (PMID 31419940, 2019).
metastatic disease (5 papers, 2019 to 2025). "Other studies have found mutations associated with metastatic disease, such as ATRX, a pseudohypoxia mRNA expression subtype, TERT alteration, and MAML3 fusion anomalies." (PMID 40445576, 2025). "Tyrosine kinase and HIF-2α inhibitors have been proposed for treatment of pseudohypoxic PCPG61, therefore, a similar rationale may be extended to C2B2 (MAML3) tumors, which have a higher propensity to develop metastatic disease." (PMID 36271074, 2022). "This study aims to investigate the potential predictive effect of known histopathological features in PCC/PGL, alongside SDHB, S100, Ki-67 proliferation index, and the expression of MAML3 and MCM6 in predicting metastatic disease." (PMID 40445576, 2025). "This study aims to explore the potential predictive effects of MAML3 and MCM6 expression, in addition to known histopathological features, SDHB, S100, and the Ki-67 proliferation index, in forecasting metastatic disease in PCC and PGL." (PMID 40445576, 2025). "Three tumors were from patients who developed metastatic disease (E205, PC, EPAS1; E206, PC, EPAS1; E235, PC, MAML3-fusion), and two tumors had locally invasive features (E007, TMEM127; E025, AT-PG, SDHA)." (PMID 36271074, 2022).
pancreatic cancer (5 papers, 2022 to 2023). "Mastermind-like 3 (MAML3) are potential therapeutic targets for small cell lung cancer and pancreatic cancer." (PMID 37389979, 2023). "Notch signaling components Jag1, Maml2, and Maml3 are direct targets of miR-200 inhibition in breast and pancreatic cancer cell lines." (PMID 36076302, 2022). "The early report reveals that MAML3 is an oncogene, and upregulation of MAML3 induced by hypoxia increases pancreatic cancer’s growth and invasion ability." (PMID 35152842, 2022). "The ability of pancreatic cancer cells to form tumor spheres was reduced through inhibition of the Notch pathway (achieved using γ-secretase inhibitors or knockdown of Jag1/Maml2/Maml3) suggesting that cell stemness of CSCs can be induced through the Notch pathway." (PMID 36076302, 2022). "Liprin-α4, MAML3 and RBPJ contributed to the proliferation, migration and invasion in pancreatic cancer 15,16." (PMID 36741255, 2023).
paraganglioma (5 papers, 2019 to 2025). A benign or malignant neoplasm arising from paraganglia located along the sympathetic or parasympathetic nerves. "Fusion genes involving MAML3 (5%), BRAF (0.6%), NGFR (0.6%), and NF1 (0.6%) have been described as genetic disease drivers in a subset of paragangliomas." (PMID 32926213, 2020).
sarcoma (5 papers, 2021 to 2025). A usually aggressive malignant neoplasm of the soft tissue or bone. "Mutations of each gene (LMO2, MAML3, MTF2, RBPMS, and SIRT1) in sarcoma were 6, 7, 6, 3, and 5%, respectively, with the most common changes in the mRNA expression." (PMID 35734428, 2022). "In order to reveal the association between the expressions of five TcoF-related genes (LMO2, MAML3, MTF2, RBPMS, and SIRT1) in the risk model and immune cell infiltration, the data on sarcoma from the TIMER database were collected." (PMID 35734428, 2022). "For instance, similar mechanisms may occur in other FET-fused sarcomas or MAML3- or NCOA2-fused sarcoma, which also contain PrLD domains." (PMID 38611033, 2024). "Round cell sarcomas with BCOR alterations usually harbor BCOR::CCNB3 and BCOR::MAML3 genetic fusions, and CIC-rearranged sarcomas are characterized by CIC::DUX4 chimeric transcript." (PMID 39021466, 2024). "Along these lines, different HOX family members were found among the most upregulated genes in a BCOR::MAML3 sarcoma when compared to Ewing sarcoma with EWSR1::FLI1 fusions and CIC::DUX4 positive sarcomas." (PMID 38611033, 2024). "BCOR immunostain is invariably positive in most BCOR-rearranged sarcomas, including the BCOR::CCNB3, BCOR::MAML3, BCOR-ITD sarcomas, and also in certain non-BCOR-rearranged sarcomas, such as YWHAE::NUTM2B sarcomas." (PMID 40705064, 2025).
neuroblastoma (3 papers, 2019 to 2022). Neuroblastoma (NB) is the most common solid, extracranial childhood tumor. "In neuroblastoma, it has been reported that MAML3 over-expression increased IGF2 transcription independently from Notch, and this mediated IGF1R activation and AKT signaling, resulting in an increased cell proliferation." (PMID 35163581, 2022). "Notably, MAML3 plays an important role in neuroblastoma progression, where it mediates the resistance to retinoic acid (RA), a drug largely used in neuroblastoma treatment, promoting hyperproliferation of tumoral cells." (PMID 33425921, 2020). "We also examined the degree of overlap between the MAML3 translocation differential gene expression signature for PPGL and that previously observed in MAML3 translocation-positive neuroblastoma tumors, and identify a significant similarity (empiric p-value: 3E-35)." (PMID 31234811, 2019).
Alpha-thalassemia (2 papers, 2018 to 2024). Alpha-thalassemia is an inherited hemoglobinopathy characterized by impaired synthesis of alpha-globin chains leading to a variable clinical picture depending on the number of affected alleles. "Molecular assessment of tumor tissue suggests somatic pathogenic variants in the genes mastermind like transcriptional coactivator 3 (MAML3), alpha thalassemia/mental retardation syndrome X (ATRX), and cold shock domain-containing E1 (CSDE1) are also associated with metastatic behavior." (PMID 38799767, 2024).
alveolar rhabdomyosarcoma (2 papers, 2021 to 2023). A rapidly growing malignant mesenchymal neoplasm. "PAX3 was the 5′ fusion partner in 29 cases with 3′ partners being FOXO1 fusions identified in alveolar rhabdomyosarcoma cases, MAML3 and NCOA1 fusions in two different biphenotypic sinonasal sarcoma cases." (PMID 34745213, 2021).
asthma (2 papers, 2017 to 2018). "SNPs in pituitary tumor–transforming 1 interacting protein (PTTG1IP) and mastermind-like 3 (MAML3) have been reported to be associated with BHR severity in adult asthma, and eQTL analyses indicate higher tissue expression with less severe BHR." (PMID 28583446, 2017). "PTTG1IP and MAML3 (pituitary tumour-transforming 1 interacting protein (PTTG1IP) and rs345983 in Mastermind-like 3 (MAML3) are novel genomewide association genes for severity of hyperresponsiveness in adult asthma." (PMID 30498567, 2018).
congenital heart malformation (2 papers, 2014 to 2016). A disease that has its basis in the disruption of heart development. "A previous GWAS finds that another SNP (rs1531070) in MAML3 is significantly (p = 4.99e-12) associated with congenital heart malformation in Han Chinese." (PMID 27790247, 2016).
endometrial cancer (2 papers, 2016 to 2019). Primary or metastatic malignant neoplasm involving the endometrium (mucous membrane that lines the endometrial cavity). "Out of 120 endometrial cancer (EC) patients, we found that those with tumors expressing higher SOX17 (n=68) had longer recurrence-free survival (P=0.024), while higher MAML3 expression (n=76) was associated with shorter recurrence-free survival (P=0.022)." (PMID 27738313, 2016). "Endometrial tumors expressing higher SOX17 levels are associated with higher recurrence-free survival rates; conversely, progression of endometrial cancer may be promoted by low SOX17 expression through downregulation of MAML3 expression and Wnt signaling." (PMID 32039004, 2019).
neuroendocrine tumor (2 papers, 2019 to 2021). "Recently, another MAML family gene, Mastermind Like Transcriptional Coactivator 3 (MAML3) has been found to be associated with hereditary paragangliomas (PGL), a type of neuroendocrine tumor that is usually derived from extra-adrenal chromaffin cells as opposed to the pituitary." (PMID 34517852, 2021).
acute lymphoblastic leukemia (1 paper, 2024). Leukemia with an acute onset, characterized by the presence of lymphoblasts in the bone marrow and the peripheral blood. "MAML3 is a transcriptional co-activator of Notch signaling pathway, contributing to cancer cells proliferation in acute lymphoblastic leukemia and some solid tumors." (PMID 38632656, 2024).
glioma (1 paper, 2022). A benign or malignant brain and spinal cord tumor that arises from glial cells (astrocytes, oligodendrocytes, ependymal cells). "ADAM17 and MAML3 are indexed in the KEGG “Notch signaling pathway”, and BMP2 and SMAD5 are indexed in the KEGG “TGF-beta signaling pathway”, which confirms our data on the involvement of these processes in the formation of glioma neurospheres." (PMID 36231068, 2022).
hypospadias (1 paper, 2019). Hypospadias is the displacement of the urethral meatus on the ventrum of the penis. "Patient 7 presented five variants in five genes: EVC, MAML3, NOTCH2, PPARGC1B and WDR11; four of them associated with hypospadias or male gonadal development and one, MAML3, with female gonadal development." (PMID 31555317, 2019).
lymph node metastasis (1 paper, 2013). "Similarly for patients with lymph node metastasis we identified four proteins, namely IL1α, XIAP, STX2, and SHKBP1, whereas for patients with liver metastasis we identified IGF1, IL1α, IGFBP2, MAML3, and SHKBP1 as significant." (PMID 24282616, 2013).
migraine (1 paper, 2025). "Our analyses revealed 283 genes, including some newly associated with migraine: MAML3, CELF4, IRX1, ASXL1, SPOCD1, CXCL, and TLR4." (PMID 41420111, 2025).
mood disorder (1 paper, 2024). A cognitive disorder a disturbance in which the person's mood is hypothesized to be the main underlying feature. "Further, genes linked to mood disorders and stress response were identified (BCAR3, FAM214A, MAML3)." (PMID 39055655, 2024).
osteosarcoma (1 paper, 2022). A usually aggressive malignant bone-forming mesenchymal neoplasm, predominantly affecting adolescents and young adults. "In contrast, the expressions of LMO2, MAML3, and SIRT1 were downregulated in all osteosarcoma cell lines." (PMID 35734428, 2022).
tumor (19 papers, 2013 to 2025). "The MAML3 protein acts as a transcriptional coactivator of NOTCH pathway associated genes, and MAML3 fusions and MAML3 overexpression are recurrent features in various tumor types." (PMID 33768452, 2021). "Collectively, this study estimated that ~ 11% of PPGL patients carry germline mutations in the four genes (SDHA, SDHB, SDHC, SDHD; SDHx) encoding SDH subunits, and ~ 5% of PPGL patients have tumor DNA carrying the novel MAML3 translocation." (PMID 31234811, 2019). "A cluster of Mastermind-like (MAML) genes, including MAML1, MAML2, and MAML3, encodes transcriptional co-activators for various signal pathways such as Notch signaling and tumor suppressor pathway activated in multiple cancers." (PMID 28249600, 2017). "The Wnt Signalling cluster, distinguished by mutations in cold shock domain-containing protein E1 (CSDE1) and somatic gene fusions of mastermind-like transcriptional coactivator 3 (MAML3), is crucial in shaping PPGLs’ tumor features." (PMID 38745767, 2024). "PD-L1 IHC in an independent series of n = 44 PPGLs confirmed that 34% (15/44) of PPGLs, 7 harboring a MAML3-fusion, exhibit PD-L1 staining in tumor cell membranes." (PMID 36854674, 2023). "This cluster is also coupled to metastatic potential, and MAML3 has been shown to drive tumor progression and increase invasive behavior in vitro." (PMID 35205664, 2022). "We identified that the alteration frequency was highest (5%) in SOX17, which is involved in oncogenesis through tumour suppression, down-regulating MAML3 expression, modulating nuclear β-catenin and antagonizing Wnt signaling." (PMID 31879572, 2019). "This suggests that MAML3 translocation has similar downstream impacts upon gene expression in these highly similar tumor types." (PMID 31234811, 2019). "Specifically, the MAML3 gene regulates the retinoic acid gene, which inhibits growth of human tumor cells." (PMID 28249600, 2017). "Our investigations revealed that SOX17 was inversely correlated with MAML3 expression in EC cell lines and tumor tissues." (PMID 27738313, 2016). "MAML3 is a nuclear protein that functions as a transcriptional co‐activator for Notch signalling, a highly conserved pathway that influences cell fate decisions, organogenesis, and tumour angiogenesis." (PMID 40432288, 2025). "Importantly, novel molecular markers were found:MAML3 (mastermind-like protein 3) fusions,SETD2 (SET domain containing 2) orATRX somatic mutations, and WNT-related expression subtype, which comprise the tumours withMAML3 fusion tumours." (PMID 29333259, 2017). "We provide evidence that SOX17 downregulates MAML3 and Wnt signaling, which may reduce tumor cell proliferation and improve patient outcome." (PMID 27738313, 2016). "Recently, various new fusion partners of BCOR have been documented, such as MAML3, ZC3H7B, RGAG1, and KMT2D, further increasing the complexity of such tumor entities, although the molecular pathogenetic mechanism remains to be elucidated." (PMID 36765856, 2023). "In vivo, PVT1 silencing repressed the tumor growth of SUP-B15 cells and reduced the expression of MAML3." (PMID 35152842, 2022). "In nude mice, SOX17 over-expression inhibited tumor growth, and co-inhibition or co-overexpression of SOX17 and MAML3 rescued this response." (PMID 27738313, 2016). "The protein profiles of nine targets, namely IGFBP2, IGF1, SHKBP1, ETS1, IL1α, STX2, MAML3, EGR3 and XIAP were verified as significant contributors to tumor classification." (PMID 24282616, 2013). "Our results suggest that decreasing SOX17 levels may promote EC development and progression, and that by downregulating MAML3 expression and Wnt signaling, SOX17 acts as a tumor suppressor that may improve outcome in patients with EC." (PMID 27738313, 2016). "The methylation of other genes, CLIP4, XKR6, CCDC57, MAML3 and SDC2, was related with one or more of the following variables: age, tumor location, and Helicobacter pylori infection, rather than with the histologic subtype." (PMID 28418867, 2017).
cancer (5 papers, 2021 to 2024). A tumor composed of atypical neoplastic, often pleomorphic cells that invade other tissues. "Primary cancer cells classified in C1 shared SNV clusters 18 and 15, including nonsynonymous mutations in transcription activator genes such as ELK4, KAT6B, and MAML3." (PMID 34507604, 2021). "The aberrant expression of MAML3 may lead to different diseases, like cancers." (PMID 35354791, 2022). "In addition, we also found that a set of 730 CpG sites located within the epi-driver genes had the same direction of change for three or more cancer subtypes, including genes that had previously proved to have biological functions in cancer progression such as EGFR, NCOR2, MAML3, TSC2, and FGFR2." (PMID 35069697, 2021).
MAML3 also shares sentences with these, for which no sentence is quoted: depression (2 papers); schizophrenia (2); alcohol dependence (1); Alzheimer disease (1); Ataxia (1); basal cell carcinoma (1); cervical cancer (1); congenital heart disease (1); duodenitis (1); Endometrial tumors (1); gastritis (1); Hypergonadotropic hypogonadism (1); hypogonadotropic hypogonadism (1); influenza (1); insomnia (1); lymphoma (1); Parkinson disease (1); Primary amenorrhea (1); prostate carcinoma (1); psychiatric disorder (1); respiratory diseases (1); sarcopenia (1); small cell lung carcinoma (1); Stroke (1); viral infection (1).